RAI14 (retinoic acid induced 14)
Description:
Plays a role in actin regulation at the ectoplasmic specialization, a type of cell junction specific to testis. Important for establishment of sperm polarity and normal spermatid adhesion. May also promote integrity of Sertoli cell tight junctions at the blood-testis barrier.
Synonyms: KIAA1334; NORPEG; RAI13; DKFZp564G013
Tractability: PROTAC: ubiquitination databases record sites on it; its protein half-life has been measured.
Gene: Protein-coding gene on chromosome 5 (34,656,328 to 34,832,612, forward strand). Ensembl gene ENSG00000039560.
Subcellular location: Cytoplasm, cytoskeleton; Cytoplasm, cytoskeleton, stress fiber; Cytoplasm, cell cortex; Cell junction; Nucleus
Subcellular location (Human Protein Atlas): Nucleoplasm; Actin filaments; Cytosol
Gene Ontology:
Molecular function: protein binding; actin binding
Cellular component: nucleoplasm; nucleus; anchoring junction; cell cortex; cytoskeleton; stress fiber
Genetic constraint (gnomAD): Loss-of-function variants: 39 observed, 98.32 expected, observed/expected ratio (o/e) 0.4, 90% interval 0.31 to 0.52. The upper end of that interval is the gene's LOEUF score, 0.52, which puts it in group 2 of 6, group 1 being the genes least tolerant of losing a copy. Missense variants: 848 observed, 1,065.7 expected, observed/expected ratio (o/e) 0.8, 90% interval 0.75 to 0.84. Synonymous variants: 328 observed, 398.66 expected, observed/expected ratio (o/e) 0.82, 90% interval 0.75 to 0.9.
Homologues: Orthologues: chimpanzee RAI14 (99% identical), macaque RAI14 (98% identical), rabbit RAI14 (91% identical), dog RAI14 (91% identical), pig RAI14 (89% identical), guinea pig RAI14 (88% identical), mouse Rai14 (85% identical), rat Rai14 (84% identical), tropical clawed frog rai14 (51% identical), zebrafish rai14 (42% identical).
Diseases named in the same sentence as RAI14 in open-access papers:
RAI14 is named in the same sentence as 31 diseases in open-access papers, as found by Europe PMC text mining. Sharing a sentence is not in itself a finding about the gene and the disease. The quoted sentences say what the papers report.
gastric cancer (14 papers, 2019 to 2024). A primary or metastatic malignant neoplasm involving the stomach. "Further, recent studies have highlighted the association between RAI14 and malignancies, such as breast cancer, gastric cancer, and prostate cancer." (PMID 32957082, 2020). "Recent studies highlight that RAI14 was up-regulated in gastric cancer associated with the patient’s prognosis and RAI14 knockdown by siRNA interference reduced proliferation and migration, promoted apoptosis through inhibiting the activation of Akt signaling pathway in gastric cancer." (PMID 32647495, 2020). "Clinical data show that tissue stiffness and expression of RAI14 and YAP are upregulated in tumor tissues and that RAI14 is strongly associated with adverse outcome in patients with gastric cancer." (PMID 39160347, 2024). "For example, several literatures have reported that RAI14 is highly expressed in gastric cancer tissues, and its expression level is correlated with the prognosis of gastric cancer patients." (PMID 36579327, 2022). "Recently, high expression of RAI14 in gastric cancer tissues, compared to matched normal tissues, was related to unfavourable patients’ prognosis." (PMID 32012980, 2020). "Instead, oncogenic activity was showed for RAI14, also named as novel retinal pigment epithelial cell gene (NORPEG), found to be aberrantly up-regulated in lung adenocarcinoma, and gastric cancer." (PMID 32012980, 2020). "The remaining prognostic genes such as OLFML2B, RAI14, SERPINE1, and MPND were also reported to be dysregulated and associated with poor prognosis in gastric cancer." (PMID 32908579, 2020). "Previous study has reported that RAI14 knockdown significantly reduced the level of the phosphorylated form p-Akt in gastric cancer cells." (PMID 31772666, 2019). "In addition, RAI14 expression in gastric cancer is also found to be positively correlated with the infiltration levels of immune cells and OS." (PMID 36934880, 2023). "In past decades, several research studies have shown that RAI14 was higher in a wide range of malignancies, containing esophageal cancer, gastric cancer, lung adenocarcinoma, ovarian cancer, and prostate cancer, and positively related to the progression of neoplasms." (PMID 35431930, 2022). "Similarly, RAI14 overexpression in breast cancer and gastric cancer were reported to be an independent predictor of poor prognosis." (PMID 32957082, 2020). "Knockdown of RAI14 suppresses the progression of gastric cancer." (PMID 32228518, 2020). "High expression of RAI14 in gastric cancer is revealed and such expression pattern could be an independent molecular predictor of poor prognosis in gastric cancer patients." (PMID 32228518, 2020). "In gastric cancer, RAI14 was highly expressed in cancer, and the high expression of RAI14 could be an independent predictor of poor prognosis in gastric cancer patients." (PMID 31772666, 2019). "Analysis of the Asian Cancer Research Group (ACRG) gastric cancer (GC) database and tissue from GC patients revealed higher expression of RAI14 in the diffuse type of GC, which has an ECM of high stiffness." (PMID 39160347, 2024). "We found that CTGF, CYR61 and RAI14 gene expression was highest in the MSS/EMT type, suggesting that three genes are consistently upregulated in gastric cancers with diffuse-type feature regardless of tumor classification (Fig. EV5H–J)." (PMID 39160347, 2024). "The mRNA levels of RAI14, GUCY1A2, CNGB3, FJX1, FZD2, ELOVL2, and GDPD4 were all expressed upregulated in gastric cancer tissues, except for CXCL13, whose expression level was not significantly different between gastric cancer tissues and normal cell lines." (PMID 36823639, 2023).
breast carcinoma (7 papers, 2019 to 2025). "In the current research, we generally investigated high-RAI14 which is associated with worse survival of breast cancer with the assistance of some databases based on bioinformatics methods." (PMID 35431930, 2022). "Furthermore, we investigated the mechanism underlying the biological effects of RAI14 on breast cancer cells." (PMID 31772666, 2019). "Recent studies have shown that the deubiquitinase STAMBP suppresses the ubiquitination of RAI14 and stabilizes its protein level, thereby promoting breast cancer progression." (PMID 39160347, 2024). "ROC curve analysis showed that RAI14 improves the diagnostic performance for CA15-3(AUCRAI14 = 0.934 vs. AUCCA15-3 = 0.836), especially embodied in early-stage breast cancer diagnosis and patients with CA15-3 negativity." (PMID 36880986, 2023). "RAI14 expression levels are also significantly upregulated during the progression of breast cancer, especially in TNBC, where RAI14 expression levels are markedly higher as detected by database analysis." (PMID 36880986, 2023). "According to the RNA-seq data in Tumor Immune Estimation Resource (TIMER), RAI14 levels were significantly different in cancer and paracancerous cells such as breast cancer cells." (PMID 35431930, 2022). "RAI14 was highly expressed in basal-like breast carcinoma [molecules expressed as ER (-)/PR (-)/HER-2 (-), equivalent to triple-negative breast cancer] than that in paracancerous tissue." (PMID 35431930, 2022). "The Kaplan–Meier plotter was used to compare the expression of RAI14 in different breast cancer subtypes." (PMID 35431930, 2022). "The relationship between RAI14 and clinicopathological parameters was further investigated using Breast Cancer Gene-Expression Miner v4.7 website." (PMID 35431930, 2022). "In various typologies of breast cancer, RAI14 levels were highly expressive in TNBC than other types (p < 0.0001)." (PMID 35431930, 2022). "We examine the expression of CPN1 and RAI14 using the Western blot in different mammary carcinoma cell lines." (PMID 35431930, 2022). "The RNA-seq data with standard processing were analyzed by using GEPIA, and the differential RAI14 levels in mammary tumor with various molecular types and paraneoplasia were obtained." (PMID 35431930, 2022). "The high expression of RAI14 is positively correlated with the malignant progression of breast cancer and suggests a worse prognosis." (PMID 31772666, 2019). "RAI14 protein was mainly localized at the cytoplasm of breast cancer cells, and the expression of RAI14 in tumor tissues was higher than that in adjacent normal tissues." (PMID 31772666, 2019). "Further, we found that RAI14 affects the proliferation, migration and invasion of breast cancer cells by regulating cell cycle and EMT." (PMID 31772666, 2019). "We examined RAI14 expression in five breast cancer cell lines (MCF7, MDA-MB-231, MDA-MB-453, T47D, and BT-549) by Western blot." (PMID 31772666, 2019). "We also found that downregulation of RAI14 can inhibit the proliferation, cell migration and invasion, which strongly suggests that RAI14 acts as an oncogene in breast cancer." (PMID 31772666, 2019). "Further, we found that knockdown RAI14 inhibits the proliferation, migration and invasion of breast cancer cells by regulating cell cycle and EMT through Akt/Cyclin D1, MMP2, MMP9 and ZEB1/E-cadhrin/Vimentin pathway." (PMID 31772666, 2019). "In this study, we found that RAI14 is highly expressed in breast cancer cell lines and breast cancer tissues." (PMID 31772666, 2019). "Our study aimed to analyze RAI14 expression in breast cancer tissue and its relevance to clinicopathological factors." (PMID 31772666, 2019). "The results showed that the expression level of RAI14 in breast cancer tissues was higher than that in normal tissues." (PMID 31772666, 2019).
breast carcinoma (continued). "Given than high expression of RAI14 is positively correlated with the malignant progression of breast cancer and suggests a worse prognosis, this finding supports a potential epigenetic mechanism through which PFOA exposure could influence BC progression." (PMID 40791616, 2025). "We subsequently validated the upregulation of RAI14 in breast cancer." (PMID 36880986, 2023). "Consequently, such discoveries indicate that RAI14 expression is associated with the level of immune infiltration in breast cancer, particularly TNBC, and provides a direction for breast cancer treatment in clinical settings." (PMID 35431930, 2022). "Relationship between mRNA expression of RAI14 and clinicopathological parameters of breast cancer." (PMID 35431930, 2022). "RAI14 is significantly upregulated in breast cancer (BRCA) than that in paraneoplastic tissues." (PMID 35431930, 2022). "In addition, the RAI14 levels in different stages of breast cancer showed high expression than normal." (PMID 35431930, 2022). "Correlation analysis between RAI14 and related genes and markers of immune cells in breast cancer." (PMID 35431930, 2022). "A higher expression level of RAI14 was found in breast cancer tissues than that in normal tissues." (PMID 35431930, 2022). "Furthermore, based on the information in GEPIA and ULCAN databases, both protein and mRNA expression of RAI14 is stimulated in breast cancer, which is compatible with the information from the TCGA database." (PMID 35431930, 2022). "The relationship between RAI14 and clinicopathological indicators was investigated at protein and mRNA levels to further determine whether RAI14 may be acted as a prospective biomarker for mammary cancer." (PMID 35431930, 2022). "In the current study, we demonstrated that RAI14 was highly expressed in breast cancer." (PMID 31772666, 2019). "Our results may provide a theoretical and experimental basis for the potential targeting of RAI14 in the diagnosis and treatment of breast cancer." (PMID 31772666, 2019). "Our study elucidates the effect of RAI14 on the development of breast cancer cells and might provide a novel target for cancer therapy." (PMID 31772666, 2019). "Our study demonstrated that RAI14 was highly expressed in breast cancer." (PMID 31772666, 2019). "Retinoic acid-induced 14 (RAI14) is involved in the development of different tumor types, however, its expression and biological function in breast cancer are yet unknown." (PMID 31772666, 2019). "Meanwhile, the RAI14 expression level was correlated with the prognosis of breast cancer patients, which indicated that RAI14 might be involved in progression of breast cancer." (PMID 31772666, 2019). "Firstly, we found that RAI14 and CPN1 are interacting proteins and explored the expression characteristics of RAI14 in breast cancer tissues by employing The Cancer Genome Atlas database." (PMID 36880986, 2023). "Furthermore, we found that RAI14 and carboxypeptidase N1 are interacting proteins and that upregulation of RAI14 expression may be involved in regulating the proliferation and invasion of breast cancer cells." (PMID 36880986, 2023). "While the expression of RAI14 was obviously elevated in TNBC, patients were more likely to develop resistance to conventional anti-BC chemotherapeutic drugs such as paclitaxel and epoetin compared to other breast cancer subtypes." (PMID 36880986, 2023). "We firstly determined the protein expression of RAI14 in 137 cases of breast carcinoma tissues and adjacent noncancerous tissues." (PMID 31772666, 2019). "Furthermore, western blotting analysis showed that knockdown of RAI14 inhibits the expression of MMP2 and MMP9 in breast cancer cells." (PMID 31772666, 2019). "RAI14 expression was higher in ER-breast cancer (p < 0.0001), while PR and HER2 status may not affect the RAI14 expression level." (PMID 35431930, 2022). "However, the expression and biological function of RAI14 in breast cancer have not been studied so far." (PMID 31772666, 2019).
lung adenocarcinoma (5 papers, 2017 to 2022). A carcinoma that arises from the lung and is characterized by the presence of malignant glandular epithelial cells. "SE associated with many new oncogenes in lung adenocarcinoma, among which, RAI14 was up-regulated in A549 and 31 of 71 patients." (PMID 29285248, 2017). "Based on the mRNA expression detected in SE-associated genes in both cell lines and tissue samples, we identified RAI14 as a novel SE-associated biomarker and potential therapeutic target in lung adenocarcinoma." (PMID 29285248, 2017). "High expression of RAI14 could inhibit cell proliferation, indicating its potential as a new biomarker for lung adenocarcinoma." (PMID 29285248, 2017). "To evaluate the possibility for clinical application, we tested the expression of DNAJB1, MCU, MPRIP, PSAP, RAI14, ZNF131 and TMC5 in 71 lung adenocarcinoma samples and paired adjacent normal tissue samples (>2 cm away from the tumor) from patients who underwent lobectomy or pneumonectomy." (PMID 29285248, 2017).
melanoma (4 papers, 2020 to 2023). A malignant, usually aggressive tumor composed of atypical, neoplastic melanocytes. "We analyzed the survival data from the R2 database and found that RAI14 high expression was associated with the poor prognosis of melanoma patients (Tumor Melanoma-Jonsson-214)." (PMID 36233342, 2022). "Here, we found that high expression of RAI14 is associated with poor prognosis in melanoma patients through the R2 database." (PMID 36233342, 2022). "Afterwards, to study the role of RAI14 in melanoma, RAI14 was effectively knocked down by sh-RAI14#1/2 for conducting loss-of-function assays." (PMID 32228518, 2020). "The human melanoma cell line MelJuSo is a good model for antigen-presenting cells and, therefore, we used these cells to confirm the interaction of Ii with Rai14 by co-immunoprecipitation experiments." (PMID 37545539, 2023). "The WB assay result showed that overexpression of RAI14 in knockdown melanoma cell lines partially restored the expression of CDK4 and CCND1." (PMID 36233342, 2022). "We further knocked down or restored the expression of RAI14 in melanoma cells by lentiviral interference technology." (PMID 36233342, 2022). "The results showed that downregulation of RAI14 significantly inhibited the cell proliferation, migration and invasion of melanoma cells, and when the expression of RAI14 was restored, the cell proliferation and migration of melanoma cells were also restored." (PMID 36233342, 2022). "Taken together, this indicates that RAI14 was essential for proliferation, migration and invasion of melanoma cells." (PMID 36233342, 2022). "MTT assays demonstrated that the silencing of RAI14 significantly inhibited cell proliferation of melanoma cells." (PMID 36233342, 2022). "Subsequently, we further confirmed the mRNA and protein expression levels of RAI14 in three melanoma cell lines, normal human epidermal melanocytes and immortalized human epidermal cells." (PMID 36233342, 2022). "The expression level of RAI14 in with-tumor melanoma patients was significantly higher than tumor-free melanoma patients." (PMID 36233342, 2022). "Then, we analyzed the expression of RAI14 in melanoma cell lines (A375, MV3 and SK-MEL-28), normal human epidermal melanocytes (Pig1) and immortalized human epidermal cells (HaCAT) by RT-PCR and Western blotting." (PMID 36233342, 2022). "We then found that the expression of RAI14 was significantly higher in melanoma than in nevus by analyzing two databases." (PMID 36233342, 2022). "Melanoma patients with high RAI14 expression have a shorter survival time than patients with low RAI14 expression." (PMID 36233342, 2022). "To explore the role of RAI14 in melanoma cells, we constructed two shRNA sequences using siRNA technology: shRAI14#1 and shRAI14#2." (PMID 36233342, 2022). "To further verify the effect of RAI14 on the proliferation and migration of melanoma cells, we constructed the RAI14 overexpression vector." (PMID 36233342, 2022). "Then, flow cytometry analysis indicated that RAI14 downregulation induced G1 arrest in melanoma cells." (PMID 36233342, 2022). "We then treated RAI14 knockdown melanoma cells with MG132 and showed that protein expression of c-MYC was rescued." (PMID 36233342, 2022). "In short, these results indicated that RAI14 knockdown suppressed cell proliferation, migration and invasion of melanoma cells in vitro." (PMID 36233342, 2022). "To explore the effect of overexpression of RAI14 on the proliferation and migration of melanoma cells in RAI14 knockdown cells, we performed an MTT assay, plate clone assay, transwell assay and WB assay." (PMID 36233342, 2022). "In summary, our study showed that RAI14 promotes cell proliferation, migration and invasion of melanoma." (PMID 36233342, 2022). "In this study, we found that the expression of RAI14 affects the proliferation, migration and invasion of melanoma cells." (PMID 36233342, 2022).